INS (insulin)
Diseases named in the same sentence as INS in open-access papers (continued):
Sharing a sentence is not in itself a finding about the gene and the disease.
Obesity (continued). "However, there was a trend to higher fasting insulin levels in KO→WT mice fed HFD suggesting that myeloid NPY deficiency increases insulin resistance with dietary obesity." (PMID 23472120, 2013). "In previous studies, a less severe model was used whereby animals were subjected to a HFD for only 8 weeks; P. balsamifera being administered from the onset of the HFD feeding in order to evaluate its potential to prevent obesity and its associated insulin resistant state." (PMID 23781256, 2013). "Adoptive transfer of MDSCs (e.g., Gr-1+ cells) into high-fat diet-fed mice improved the response of the recipient mice to insulin while, in contrast, MDSCs depletion (after treatment with anti-Gr-1 antibody) increased their susceptibility to obesity and further worsened their resistance to insulin." (PMID 24455420, 2013). "The most popular hypothesis explaining the association between obesity and cancer is that of lower insulin sensitivity." (PMID 24073332, 2013). "Given their relative hyperinsulinemia, AA may be particularly sensitive to the effects of both diet and insulin sensitivity on risk for obesity." (PMID 23298367, 2013). "Metabolic profiles have been shown to be associated to obesity status and insulin sensitivity." (PMID 24330454, 2013). "The metabolic alterations associated with obesity, including changes in insulin and insulin-like growth factor binding protein 1 (IGFBP-1) serum levels (which result in increased circulating free IGF-1 levels), are also significantly correlated with breast cancer recurrence and mortality." (PMID 23880059, 2013). "Collectively, the data suggest that insulin resistance may be causal to depressed mood during obesity while increasing sensitivity to insulin has antidepressant actions." (PMID 24109426, 2013). "Furthermore, these knock out models display reduced macrophage infiltration into insulin sensitive organs along with reduced cytokine secretion from BMM indicating a potential role for IL-1β in maternal UN-mediated obesity and associated co-morbidities." (PMID 23844177, 2013). "On the other hand, it is well-known that the gene expression of adipogenic genes (both lipogenic and insulin signaling-related genes) is positively linked to adipose tissue expandability (lipid storage capacity) and to protection from developing obesity-related metabolic disturbances." (PMID 23951013, 2013). "Furthermore, in a diet-induced model of obesity the data has shown that insulin-mediated NO release is blunted in the early development of obesity, which is believed to be associated with increased endothelial cell-derived ROS." (PMID 24252331, 2013). "In pre-adipocytes, resveratrol down-regulates PPAR-γ expression (a nuclear hormone receptor, regulating adipocyte differentiation, insulin sensitivity and obesity susceptibility) and increases expression of genes modulating mitochondrial activity (SIRT3, uncoupling protein 1, mitofusin 2)." (PMID 23698776, 2013). "Obesity is associated with vascular changes, impaired insulin regulation, and reduced cardiovascular fitness, which all might contribute to decreased cognitive function." (PMID 23570390, 2013). "However, the structure and biology of resistin differ substantially between species, and many aspects, specifically its association with obesity and its effects on insulin sensitivity in humans, remain controversial." (PMID 24072088, 2013). "However, other studies have not found associations between this polymorphism and metabolic rate, obesity, BMI, insulin secretion or T2DM." (PMID 23365654, 2013). "The therapeutic effects of central leptin gene therapy have been reported in insulin-deficient diabetes and in obesity animal models, such as ob/ob, diet-induced obese mice, insulin-deficient type 1 diabetes mice, and insulin-dependent diabetes animals (Akita mice)." (PMID 23579596, 2013). "This reduction could lead to changes in insulin sensitivity and promote obesity-associated inflammation." (PMID 24369540, 2013).
Obesity (continued). "Repeated reduced insulin response has been associated with reduced incidence of obesity and T2D." (PMID 23088297, 2012). "Other risk factors, such as dyslipidemia and obesity in OLETF or weight gain in insulin injected GK, may also contribute to the endothelium dysfunction." (PMID 21977022, 2012). "Therefore, we investigated the associations of low serum amylase with plasma insulin levels, and obesity-related parameters, including leptin." (PMID 22748134, 2012). "Thus, kinin B1 receptor participates in the modulation of insulin action in adipocytes, contributing to systemic insulin sensitivity and predisposition to obesity." (PMID 23024762, 2012). "At that stage of our work, we hypothesized that IL-7 might impact on WAT mass increase and metabolic dysfunctions associated with the development of obesity, such as insulin and glucose intolerance." (PMID 22768283, 2012). "Insulin has long been regarded as a possible mediator of the effects of obesity and physical inactivity on colorectal cancer risk, since, in addition to its role in metabolism, insulin has mitogenic and anti-apoptotic activity." (PMID 22127286, 2012). "HFD-induced hypothalamic inflammation is suggested to be involved in the development of obesity and its associated secondary complications, with inflammation occurring centrally before systemic inflammatory markers are detected and insulin and leptin resistance are incurred." (PMID 23145019, 2012). "To test this hypothesis, we characterized muscle SOCS3 expression in response to metabolic challenges known to be associated with insulin and/or leptin resistance such as high-fat diet feeding, genetic obesity, lipid infusion, and TNFα injection." (PMID 23115649, 2012). "Since insulin-resistant conditions such as obesity and DM2 are associated with low HDL-C and generation of smaller HDL particles, the relative increase in HDL apoC-III may change the HDL particle’s protective functions." (PMID 22898077, 2012). "It is worthwhile to note the role played by visfatin in mediating insulin sensitivity, and this prominent adipocytokine may well prove to be an important mechanistic link in the network of factors affecting obesity-associated tumor growth." (PMID 23170114, 2012). "Furthermore, mice homozygous for disruptions in this gene display resistance to diet-induced obesity (depending on the allele), showing decreased adipose tissue and improved glucose tolerance and insulin sensitivity." (PMID 22498030, 2012). "To gain insight in the relationship between intestinal permeability and obesity-associated metabolic disturbances in humans, we hypothesized a possible association between circulating zonulin, obesity and insulin sensitivity according to glucose tolerance." (PMID 22629362, 2012). "Furthermore we show that muscle myostatin mRNA content is associated with impaired insulin sensitivity, increased triglycerides, and low-grade chronic inflammation as well as obesity and a poor fitness level." (PMID 22615949, 2012). "Although fatty acid oxidation is strengthened in insulin-sensitive organs, including adipose tissue and skeletal muscle in KO mice fed an HF, increased obesity and body weight maybe associated with the increased food intake induced by RGS5 deletion." (PMID 22272317, 2012). "Besides, the excess of plasma non esterified fatty acid (NEFA) associated with obesity has been extensively pointed out as the main cause leading to the insulin-resistant state and development cardiovascular complications secondary to chronic overweight." (PMID 22457831, 2012). "In line with previous reports, we report here that inhibition of 11β-HSD1 by BVT.2733 could not only prevent the development of obesity, but also cause rapid weight loss and improve glucose tolerance and insulin levels." (PMID 22768329, 2012).
Obesity (continued). "Among the 32 probesets, Scd1 is remarkable in that Scd1-deficient mice show the metabolic phenotypes in accordance with those observed in Cdkal1−/− mice; e.g., decreased susceptibility to diet-induced obesity, decreased plasma insulin level, and improved glucose tolerance." (PMID 23173044, 2012). "This strategy has been used to great effect in other complex disorders; for example, following discovery of loci for T2DM, a binary outcome, signals have been refined by studying continuous traits associated with the disease such as fasting glucose, insulin secretion, and obesity." (PMID 22400124, 2012). "Obesity is associated with low-grade chronic inflammation attributed to dysregulated production, release of cytokines and adipokines and to dysregulated glucose-insulin homeostasis and dyslipidemia." (PMID 22848362, 2012). "Thus, mice with Per2 gene mutation show altered glucose homeostasis and compromised insulin-stimulated NO release, independently of obesity." (PMID 22934083, 2012). "Since the proteins involved in ER stress-related unfolded protein response were down-regulated, they may induce resistance to insulin and play an important role in the development of obesity associated with the metabolic syndrome." (PMID 22998770, 2012). "Lower levels of adiponectin are often associated with obesity and insulin resistant states." (PMID 23285120, 2012). "Some have postulated that exogenous insulin therapy in T2DM might be associated with DPN through an exacerbation of obesity, fluid retention, hypertension and hyperlipidemia." (PMID 22642973, 2012). "Acquired disruption of brain insulin action may confer risk for and/or underlie “food-abuse” disorders and the recalcitrance of obesity." (PMID 21969871, 2011). "Thus, exposure to an increase in high maternal glucose and insulin concentrations from conception results in a larger and fatter infant who is at increased risk of obesity in later life." (PMID 22203829, 2011). "Importantly, improvement in glucose-insulin homeostasis in obese TSP1 deficient mice was observed even though mice exhibited similar levels of obesity as wild type controls." (PMID 22039525, 2011). "Indeed, the progression to T2D in humans with obesity is largely due to insulin secretory dysfunction and significant loss of functional β cells." (PMID 22164157, 2011). "Since obesity has become an epidemic health issue, researchers have found that obesity, particularly abdominal obesity, is associated with resistance to the effects of insulin on peripheral glucose and fatty acid utilization, often leading to type 2 diabetes mellitus." (PMID 21960997, 2011). "In addition to leptin, other obesity-related factors are linked to AD including insulin, changes to the cerebral vasculature, and direct lipotoxicity." (PMID 22013440, 2011). "The beneficial effects of FOS supplementation (decrease in hyperglycemia, improvement of insulin sensitivity) in animal models of obesity are reported to be partly linked to an increased expression of proglucagon and production of glucagon-like peptide-1 by endocrine L-cells present in the colon." (PMID 21707971, 2011). "Likewise, deletion of S6K1 alleles increases insulin sensitivity and protects mice against age- and diet-induced obesity." (PMID 20167101, 2010). "The negative relationship between fasting ghrelin concentration and obesity might be explained by an inhibitory effect of insulin on ghrelin, since a higher IR is associated with visceral fat accumulation." (PMID 20537155, 2010). "This gives us a speculative clue that may suggest that the mechanism of increased FGF-21 levels in cardiovascular disease is similar to obesity-associated resistance to insulin." (PMID 21206918, 2010). "Since the minor allele of SNP rs6232 was associated with higher insulin sensitivity in our study and with obesity in a large metaanalysis including more then 13,000 subjects, we hypothesize that this allele may promote a kind of obesity, which is more benign." (PMID 20534142, 2010).
Obesity (continued). "Since BMI, obesity and insulin level are well known risk factors for CRC, the two SNPs may indirectly affect cancer risk." (PMID 20920174, 2010). "Furthermore, Scd-1 deficient mice were found to be resistant to diet-induced obesity and characterized by decreased body weight, improved insulin sensitivity, and decreased hepatic steatosis." (PMID 20565855, 2010). "Moreover, IL-7 treatment also greatly improved obesity-associated disorders with a complete restoration of insulin sensitivity, and a partial improvement of the glucose tolerance in adulthood." (PMID 20376352, 2010). "In addition, these subjects had low cortisol levels and showed signs of obesity-associated metabolic strain, including higher levels of insulin and inflammatory markers." (PMID 19804639, 2009). "Studies suggest elevated endotoxin levels may arise as a result of obesity related hyperinsulinemia; hence low-grade endotoxinemia may be caused by the effect of insulin on intestinal motility and/or intestinal permeability." (PMID 19368716, 2009). "A causal role of miR17-5p and miR-132 in obesity related impaired insulin sensitivity is suggested by the result that both miRNAs are significantly related to lower visceral fat mass, lower circulating parameters of chronic glycemia as well as improved insulin sensitivity." (PMID 19259271, 2009). "The inhibition of 11β-HSDl indicates that LXR might be involved in suppressing glucocorticoid effects, which might lead to reduced development of obesity and improved insulin sensitivity linked with glucocorticoid activity." (PMID 20046702, 2008). "Similarly, in hormones, leptin (P≤ 0.001), insulin (P≤0.001) and glucagon (P≤0.001), and GH (P=0.003) were associated with obesity." (PMID 20300294, 2008). "Genetic variants modulating insulin action may have an increased effect on T2D susceptibility in the presence of obesity, whereas genetic variants acting on insulin secretion may have a greater impact on T2D susceptibility in non-obese individuals." (PMID 18498634, 2008). "Furthermore, Fsp27−/−and Fsp27/lep double-deficient mice are resistant to diet-induced obesity and display increased insulin sensitivity." (PMID 18682832, 2008). "There is some evidence that hormones may modify the association of obesity with colon cancer in women, as oestrogen may increase susceptibility to the carcinogenic effects of higher insulin levels associated with obesity." (PMID 18728645, 2008). "In conclusion, from these cross-sectional analyses of middle-aged Japanese men, we found a positive association between the fasting serum insulin concentration and weight fluctuation that occurred from young adulthood even after adjustment for the degree of obesity." (PMID 17827860, 2007). "The mechanism by which oestrogens enhance the positive association was hypothesised to be upregulation of insulin growth factors, which leads to an increase in obesity-induced levels of insulin, and thereby increases CRC risk." (PMID 17987040, 2007). "In rats and mice HFD causes obesity andincreases plasma insulin, glucose, and leptin levels." (PMID 17389764, 2007). "However, we have some circumstantial evidence of a functional link as we recently found that a polymorphism in the FTO gene, which is related to obesity, is associated with a decreased insulin effect on cerebrocortical beta activity." (PMID 18030331, 2007). "High fatty diets together with alcohol, inadequate consumption of fruits and vegetables, nutritional habits containing low roughage and rich in carbohydrates lead to obesity; consequently, they increase the risk of breast cancer by raising the level of insulin and estrogen in the bloodstream." (PMID 19319213, 2007). "Although other unknown metabolic mechanisms cannot be excluded, it is likely that the obesity caused by the combination of high-carbohydrate diet and insulin in this case contributed to the patient's deteriorating kidney function." (PMID 16774676, 2006).
Obesity (continued). "Moreover, BPA combined with insulin favors the conversion of fibroblasts to adipocytes, enhancing the risk of obesity, a metabolic disorder that has been related to endocrine disruptors in the last years." (PMID 16393666, 2006). "In addition, Pparg agonists are generally associated with promoting insulin sensitization in the context of obesity." (PMID 15760467, 2005). "This discrepancy might be due to an obesity-dependent effect of the "at risk" allele on insulin sensitivity." (PMID 15784141, 2005). "Fasting insulin (INS) associated mainly with obesity and lipids factors." (PMID 15656912, 2005). "Normal-sized, more insulin-sensitive adipocytes have been associated with early onset of obesity." (PMID 15530168, 2004). "Through its adverse impact on insulin action, obesity is a major risk factor for the disease." (PMID 14551916, 2003). "Furthermore, there is a significant relationship between liver disturbances, hypertension, and T1D, primarily through mechanisms involving insulin resistance, metabolic dysfunction, and systemic inflammation, often linked to metabolic syndrome components like obesity/overweight." (PMID 41596635, 2026). "Additionally, omega-3 fatty acids exhibit anti-inflammatory properties that may positively influence metabolic health, including lipid profiles, insulin sensitivity, and obesity-related risk factors in children." (PMID 42042214, 2026). "Moreover, diets high in simple carbohydrates (such as refined sugars and ultra-processed products), are directly associated with a greater risk of overweight and obesity as they can cause spikes in glucose and insulin, which promote fat storage and insulin resistance." (PMID 41049363, 2025). "Similarly, glucose and insulin tolerance were worsened with obesity but improved by weight loss." (PMID 40654836, 2025). "Additionally, fruits, particularly those with high glycemic indices, contain natural sugars such as sucrose, fructose, and glucose, which can cause spikes in blood sugar and insulin levels; overconsumption of these simple sugars is a significant contributor to obesity and related diseases." (PMID 40004777, 2025). "In summary, our results emphasize that dietary antioxidants may influence the relationship between TNF-α -308 G/A gene polymorphisms and insulin levels in individuals with obesity by mitigating oxidative stress, which may help reduce the effects on inflammatory pathways." (PMID 40732969, 2025). "The chronic increase in free fatty acids associated with obesity may increase insulin demand by pancreatic beta cells and induce intrinsic beta cell dysfunction through endoplasmic reticulum (ER) stress, which is associated with beta cell loss during the development of T2D." (PMID 40561274, 2025). "On the other hand, BMI is closely linked to MetS, obesity can lead to adipose tissue dysfunction, prompting adipocytes to secrete inflammatory cytokines and adipokines, which may disrupt insulin signaling pathways and impair glucose and lipid metabolism, thereby increasing the risk of MetS." (PMID 41171818, 2025). "Notably, the plant did show a significant improvement in insulin sensitivity, indicating that this could be a key mechanism underlying its potential anti-obesity effect." (PMID 40343290, 2025). "While animal models and small-scale human studies support this pathway, its translational relevance remains unclear, and the impact of vitamin D on insulin secretion may be overshadowed by other metabolic stressors such as obesity, inflammation, and genetic predisposition." (PMID 40863099, 2025). "Experimental models indicate that obesity-associated mitochondrial ROS and mPTP opening in the hippocampus and the prefrontal cortex impair synaptic plasticity, reduce long-term potentiation, and disrupt insulin and BDNF signaling, thereby affecting learning, memory, and emotional regulation." (PMID 41465437, 2025).